MYC (MYC proto-oncogene, bHLH transcription factor)
Diseases named in the same sentence as MYC in open-access papers (continued):
Sharing a sentence is not in itself a finding about the gene and the disease.
B-cell lymphoma (continued). "High grade B-cell lymphoma with MYC and BCL2 rearrangements (HGBL-DHL), formerly termed double-hit lymphoma (DHL) which constitutes 5–10% of histologically diagnosed diffuse large B-cell lymphoma (DLBCL), is currently classified as a unique and separate entity." (PMID 33777762, 2021). "Similarly, mouse models of MYC-rearranged B-cell lymphoma and ALK-rearranged NSCLC displayed highly penetrant phenotypes, precluding the study of the stochastic events driving cancer growth." (PMID 34585724, 2021). "In addition, in a subset of so called double- or triple-hit B-cell lymphomas concurrent translocations involving MYC and BCL2 and/or BCL6 occur." (PMID 34210001, 2021). "Initially, in murine B cell lymphoma it was found that FOXO is an antagonist of MYC." (PMID 34372899, 2021). "To further explore the association of MYC and CXCR4 expression, we analyzed patient datasets and found a significant correlation of MYC mRNA and IG-MYC translocation status with CXCR4 mRNA expression in B-cell lymphoma patients." (PMID 34363012, 2021). "Therefore, our data suggested that AID is a poor prognostic marker of High-grade B-cell lymphoma with MYC and BCL2 and/or BCL6 rearrangements, as it has a different pathological background." (PMID 34945004, 2021). "Additionally, key microRNAs (miRs) (such as miR-34a and miR17-92) are related to MYC activation and play a vital role in some B-cell lymphomas." (PMID 32549409, 2020). "Furthermore, a recent report on Ibtk shows that its haploinsufficiency also alters tumor microenvironment by enhancing MYC-driven vascularization in B-cell lymphomas." (PMID 32549409, 2020). "High-grade B cell lymphomas with rearrangements on C-MYC and BCL2 and/or BCL6 (HGBL with MYC and BCL2 and/or Bcl6 rearrangement) are associated with worse clinical outcomes and thus were introduced as a separate new category in the recently updated WHO classification." (PMID 32613279, 2020). "The genetic alteration of MYC may suffice as this secondary alteration, leading to the transformation into a high-grade B cell lymphoma." (PMID 32102485, 2020). "Notably, BMI-1 has been one of the first genes initially identified as an oncogene that cooperates with MYC in the generation of mouse pre-B-cell lymphomas by inhibiting INK4a/ARF proteins and by activating the human telomerase reverse transcriptase (h-TERT)." (PMID 32549409, 2020). "The prognostic implications of DHL and THL underlie the 2017 World Health Organization (WHO) update, which includes the cytogenetically defined category of “High grade B cell lymphoma with MYC and BCL2 and/or BCL6 rearrangements” (DHL/THL) as its own distinct entity." (PMID 31932576, 2020). "MYC rearrangements have a high frequency in the aggressive B-cell lymphomas." (PMID 32549409, 2020). "MYC rearrangements usually confer aggressive biological behavior to large B-cell lymphomas." (PMID 32260556, 2020). "Furthermore, the analysis of lncRNA expression in P493-6 B-cell lymphoma cells with either high or low MYC levels led to the identification of 498 MYC-regulated lncRNAs." (PMID 33134177, 2020). "Therefore, diagnosis of a high-grade B-cell lymphoma with MYC and BCL2 rearrangements that transformed from a low-grade follicular lymphoma was rendered." (PMID 32183313, 2020). "Previously, let-7 family miRNAs were found to be widely repressed by c-MYC in B cell lymphoma." (PMID 33168041, 2020). "In B-cell lymphomas, MYC gene can be inserted in various positions of the IgH locus." (PMID 32549409, 2020). "Using the Eμ-Myc mouse model of spontaneous MYC-driven B-cell lymphoma, we showed that progression from premalignancy to malignancy in vivo is associated with UBTF-dependent epigenetic remodeling that activates a significant proportion of previously pseudo-silent rDNA repeats." (PMID 30701204, 2019).
B-cell lymphoma (continued). "To shed light on this phenomenon, we investigated the different modes of actions of MYC in aggressive B-cell lymphoma cell lines subdivided into three groups: (i) MYC-positive BL, (ii) DLBCL with MYC translocation (DLBCLpos) and (iii) DLBCL without MYC translocation (DLBCLneg) for control." (PMID 30953469, 2019). "Indeed, high-grade B-cell lymphomas with chromosomal breakpoints affecting the MYC locus in combination with breakpoints involving the BCL2 or BCL6 genes, constitute a separate entity frequently called “DH lymphomas”1." (PMID 30926794, 2019). "A previous preclinical study investigating the role of Chk1 expression in MYC amplified tumours has in fact shown that its blockade resulted in caspase-depended apoptosis of the MYC-overexpressing tumours cells both in vitro and in murine models of B-cell lymphoma." (PMID 30746633, 2019). "On these bases we performed a “real life” retrospective multicenter study with the aim of characterizing the clinical and pathological landscape of MYC rearranged aggressive B-cell lymphomas in Italy, and comparing for efficacy the preferred therapeutic choices." (PMID 31976479, 2019). "Although downregulation of the DZ program by FOXO1 knockdown in a MYC-driven mouse B cell lymphoma model that harbored a constitutively active version of the PI3K catalytic subunit has been recently reported, the repertoire of repressed genes was different from what we obtained in human cell lines." (PMID 31557894, 2019). "The poor outcome of high-grade B-cell lymphoma, with rearrangements of MYC, BCL2 and/or BCL6, also known as double-hit lymphoma or triple-hit lymphoma (DHL or THL), has been well documented, while the clinical significance of extra copies of MYC, BCL2 or BCL6 are still less well known." (PMID 31315646, 2019). "In recognition of its unique biology and clinical behavior, DHL has been included in the 2016 revision of the World Health Organization (WHO) classification of lymphoid neoplasms as a new category of “high-grade B-cell lymphoma (HGBL) with MYC and BCL2 or BCL6 rearrangements”." (PMID 30323893, 2018). "This enzyme could contribute to the gain of chromosomal aberrations that affect cell cycle-regulator genes, such as c-MYC; acting together, these mechanisms could lead to the development of aggressive B-cell lymphomas in HIV+ patients." (PMID 30337929, 2018). "We found that MYC-related signatures are directly related to MYC protein expression across the whole spectrum of B-cells and B-cell lymphoma, suggesting that the MYC-responsive machinery shows predominantly quantitative, rather than qualitative, modifications in B-cell lymphoma." (PMID 30038718, 2018). "The unregulated expression of c-MYC in GC B-cells leads to the bypass of affinity-based selection and perpetuation of the GC re-entry that significantly increases the chances of oncogenic genetic events for the development of B-cell lymphoma." (PMID 28379189, 2017). "Therefore, the MYC-induced transcriptional program strongly influences lncRNA expression in MYC-positive B-cell lymphomas." (PMID 28704924, 2017). "However, there is a correlation between c-MYC expression by IHC and c-MYC gene abnormalities in aggressive B-cell lymphomas." (PMID 28379189, 2017). "In addition, the Authors analyzed lncRNA differentially expressed in B-cell lymphoma with high and low MYC levels." (PMID 28947998, 2017). "Indeed, some studies have shown that B-cell lymphomas with concurrent MYC and BCL2 abnormalities, other than translocations, appear to behave similarly to MYC/BCL2 double-hit lymphomas." (PMID 28212447, 2017). "MYC dysregulation is characteristic of several types of B cell lymphomas." (PMID 28375188, 2017).
B-cell lymphoma (continued). "As BCL2 rearrangement is the one of the two “hits” in double-hit lymphoma, acquisition of c-MYC rearrangement during disease progression leads to histologic transformation to high-grade B-cell lymphoma/DHL and rarely plasmablastic lymphoma or blastoid transformation of FL/B-lymphoblastic lymphoma." (PMID 28379189, 2017). "Genes up-regulated in B cell lymphoma tumors expressing an activated form of MYC [GeneID=4609]." (PMID 28423528, 2017). "While c-MYC rearrangement is typically associated with an inferior prognosis and poor response to therapy in DLBCL, the clinical significance of c-MYC rearrangement in the low-grade B-cell lymphoma is less clear and should be interpreted in the context of overall cytogenetic changes." (PMID 28379189, 2017). "Furthermore, CDK9 inhibition by dinaciclib treatment has been shown to induce apoptotic responses in aggressive MYC-driven B-cell lymphoma through transcriptional blockage of MCL-133." (PMID 28361959, 2017). "Besides B-cell lymphoma, the oncogene MYC is known to be overexpressed also in colorectal cancer (CRC), where it plays an important role in tumor progression downstream of the WNT signaling pathway." (PMID 28704924, 2017). "MYC/BCL2 DHL has been well studied in the literature and yet no studies have systemically compared the clinicopathologic features of patients who present with de novo disease versus patients with a history of low-grade B-cell lymphoma, mostly FL, and then develop MYC/BCL2 DHL." (PMID 27203548, 2016). "Finally, CCT245737 also showed significant single-agent activity against a MYC-driven mouse model of B-cell lymphoma." (PMID 26295308, 2016). "However, most of what we know about double-hit B-cell lymphoma is derived from studies of the most common form, MYC/BCL2 DHL." (PMID 26573234, 2016). "MYC had been reported to cooperate with cyclin D1 to develop B cell lymphoma in transgenic mice." (PMID 26517511, 2015). "Aurora kinases are upregulated by MYC and seem to be important in MYC-driven B-cell lymphoma." (PMID 26393619, 2015). "MYC, one of the major oncogenes in B-cell lymphoma, has also been affected by MPT0E028." (PMID 25669976, 2015). "BL is a germinal center–derived aggressive B-cell lymphoma with frequent MYC translocation." (PMID 25613729, 2015). "Depletion of PRPS2 levels by siRNA in c-MYC-driven B-cell lymphomas improved survival and induced complete tumor regression in 30 % of mice, strongly indicating that protein and nucleotide biosynthesis controlled by PRPS2 is crucial for c-MYC-driven tumorigenesis." (PMID 26654227, 2015). "Furthermore, malignancies harboring c-MYC upregulation, such as small cell lung cancer and various B cell lymphomas, exhibit high miRNAs 17-92 levels, proving that miRNAs 17-92 cluster is under c-MYC control." (PMID 25593996, 2014). "This B-cell lymphoma line expresses the human c-MYC protein in a B-cell specific fashion." (PMID 24130880, 2013). "Furthermore, human c-MYC-reactive animals are protected from lethal doses of B-cell lymphoma cells over-expressing human c-MYC." (PMID 24130880, 2013). "It was also shown that c-MYC promotes their transcription and, interestingly, enforced expression of the mir-17-92 cluster acted with c-myc to accelerate tumour development in a mouse B-cell lymphoma model." (PMID 17716371, 2007). "Clear associations between phenotypes and genetic subtypes (e.g., MCD with extranodal sites or EZB-MYC and high-grade B-cell lymphoma (HGBCL)/DLBCL with MYC and BCL2 double hits) suggest that these differences may be related to the inherent heterogeneity of DLBCL and the selection of cohorts." (PMID 40067847, 2025). "We propose that MYC rearrangement might play a role in the varying levels of immaturity seen in B-cell lymphoma/leukemia, irrespective of cell origin or other gene mutations." (PMID 41142614, 2025).
B-cell lymphoma (continued). "The initial diagnostic approach of aggressive peripheral B-cell lymphomas should include the evaluation of the morphological and immunophenotypic characteristics including, as previously discussed, the COO and the percentage of MYC and BCL2-positive neoplastic cells." (PMID 39684922, 2024). "Aggressive B-cell lymphomas with the genetic rearrangements of MYC, BCL2 and BCL6 may show either a blastoid morphology or an intermediate morphology between Burkitt lymphoma (BL) and DLBCL or, in half of cases, may be morphologically indistinguishable from DLBCL, NOS." (PMID 39684922, 2024). "Considering the known function of HSP90 in mediating MYC stability and work that postulated HSP90 as a drug target in MYC-driven B-cell lymphoma, we hypothesized that a coordinated regulation between HSP90 and MYC (and its targets) drives the development of CAR-T resistance." (PMID 38326887, 2024). "However, the negative TdT and expression of BCL6 in a subset of malignant cells raise the possibility of a high grade B-cell lymphoma with MYC and BCL2 rearrangements or a lymphoblastic transformation of follicular lymphoma, although there is no clinical evidence to support these diagnoses." (PMID 38175445, 2023). "Moreover, given that a pharmacological inhibition of c-MYC is difficult, inhibition of DDX3X or DDX3Y could represent alternative therapeutic avenues for the treatment B-cell lymphoma in male patients with DDX3X LOF mutations." (PMID 37035206, 2023). "Indeed, the use of a specific inhibitor targeting GLS leads to an inhibition of MYC-induced B-cell lymphoma and MYC-induced hepatocarcinoma, while, GDH inhibition results in lower α-KG levels and high ROS production, resulting in hindering of cancer cell proliferation and tumor progression." (PMID 34249759, 2021). "In addition, our data suggest the differential expression of non-coding RNAs that regulate pro-apoptotic pathways may be key to understanding IL-6-mediated survival of MYC-driven B cell lymphoma." (PMID 33651821, 2021). "Although Burkitt lymphoma is a hallmark of MYC-induced B-cell lymphoma in humans, mice models with induced MYC in their lymphoid lineage could not completely turn to Burkitt lymphoma." (PMID 34372899, 2021). "A deeper understanding of the molecular mechanisms of MYC roles and its interactors in each B-cell lymphoma types provides a wide set of candidates for the development of a better personalized targeted therapy that in near future could lead to successful treatments with less toxicity." (PMID 32549409, 2020). "Here, we have highlighted the transcriptional regulation network of MYC during lymphomagenesis, the molecular mechanisms of MYC collaborations that lead to escape from apoptosis, and the circuits between MYC and miRs involved in the pathogenesis of B-cell lymphomas harboring MYC alterations." (PMID 32549409, 2020). "Thus, the global incidence of MYC rearrangements in large B-cell lymphomas (LBCL) being low, it is necessary to clarify whether FISH or other methods have to be applied to all LBCL or just in selected cases." (PMID 32260556, 2020). "In order to identify MYC-regulated lncRNAs possibly involved in lymphomagenesis, Doose and colleagues examined RNA-sequencing data of patients from the major subtypes of mature B-cell lymphomas, namely BL, DLBCL, and FL, compared with data from healthy GC B-cells." (PMID 28947998, 2017). "Therefore, the low co-expression of BCL2/MYC in our series of cases could explain our observation of the favorable prognosis of B-cell lymphomas involving WR." (PMID 28086220, 2017). "Moreover, recently a ‘mutual negative feedback loop’ involving MYC and miR-548m was described in non-Hodgkin B-cell lymphomas, in that this regulatory loop is important for sustaining a high level of MYC and low level of miR-548m during lymphomagenesis and drug resistance." (PMID 26580398, 2015).
B-cell lymphoma (continued). "Thus it might be of interest to determine the recurrence of MYC/LRMP rearrangements in a larger number of B-cell lymphomas." (PMID 23171647, 2012). "Histopathology revealed B-cell non-Hodgkin lymphoma, confirmed by immunohistochemistry (CD20+, BCL2+, BCL6+, MUM1+, and c-MYC+)." (PMID 42221471, 2026). "Although c-MYC signaling is associated with aggressive neoplasms, we recently demonstrated the prevalence of c-MYC/PLK1 signaling in nodular lymphocyte predominant B-cell lymphoma (NLPHL), an indolent B-cell lymphoma subtype." (PMID 41008822, 2025). "The IGH locus is a frequent translocation partner for MYC and BCL2 genes in B-cell lymphomas, driving oncogenic overexpression that promotes uncontrolled proliferation (MYC) and inhibits apoptosis (BCL2)." (PMID 41301875, 2025). "In our study, we identified two subtypes of LBCL: diffuse large B-cell lymphoma (DLBCL) (n = 19, 90%) and high-grade B-cell lymphoma (HGBL) (n = 1, 5%) with MYC and BCL2 rearrangements." (PMID 39379648, 2025). "Clinical, cytogenetic, and immunophenotypic manifestation of aggressive B-cell lymphomas and B-ALL with concomitant MYC rearrangement in our hospitals." (PMID 41142614, 2025). "Conventional cytogenetics analysis identifies patients with translocation of MYC and BCL2 and/or BCL6 as a subgroup of aggressive B-cell lymphoma with poor prognosis and phenotypic proximity to Burkitt lymphoma." (PMID 41364305, 2025). "The classic scenario is in mature B-cell lymphomas, such as Burkitt lymphoma, in which the IGH enhancer activates MYC, or follicular lymphoma, in which the IGH enhancer activates BCL2." (PMID 41228256, 2025). "DLBCL with rearrangements of MYC, BCL2, and/or BCL6, known as “double-hit lymphoma” (DHL), has been defined as a new entity and renamed “high-grade B-cell lymphoma (HGBCL) with rearrangements of MYC and BCL2 and/or BCL6”." (PMID 38918775, 2024). "High-grade B-cell lymphomas with MYC and BCL2 and/or BCL6 rearrangements are known for their aggressive clinical course and so are the ones with MYC and BCL2 protein overexpression." (PMID 38397877, 2024). "Therefore, EBF1, PAX5, and MYC lesions may drive B-cell malignancy and induce B-cell lymphomas." (PMID 38318177, 2024). "In the differential diagnosis, BL needs to be differentiated from other high-grade NHLs, including high-grade B-cell lymphoma, with both MYC and BCL-2, and/or BCL-6 translocations, as well as diffuse large B-cell lymphoma (DLBCL) with MYC translocation." (PMID 39720565, 2024). "This case describes a complex example of an aggressive TdT‐positive high‐grade B‐cell lymphoma (HGBCL), with MYC and BCL2 rearrangements transformed from follicular lymphoma marked by significant tissue involvement and a concurrent leukemic phase." (PMID 39691256, 2024). "All cases were successfully tested for common breakapart molecular events for B-cell lymphomas and PCNLs, BCL6, BCL2, CCND1, IGH, IGL, IGK, and MYC." (PMID 38730692, 2024). "In WHO-HAEM5, tumors with MYC and BCL2 rearrangements are named diffuse large B-cell lymphoma/high-grade B-cell lymphoma with MYC and BCL2 rearrangements (DLBCL/HGBCL MYC/BCL2)." (PMID 36460764, 2023). "Overexpressed MALAT1 interacts with EZH2 which is highly expressed in B-cell lymphomas, facilitating the complex binding to MIR-150 promoter region which increases MYC expression." (PMID 37182123, 2023). "Objective responses were seen across DLBCL subtypes, including activated B cell, germinal center B cell and high-grade B cell lymphoma double hit (HGBL-DH, with MYC and BCL2 rearrangements) subtypes." (PMID 37857711, 2023). "Taken together, SC-1 represents a triple-hit B-cell lymphoma cell line, in which IGH rearrangements target FL-specific oncogene BCL2, MYC, as well as a novel target at 17q21, together with fusion of BCL6 and MBNL1." (PMID 37371852, 2023).